TNF (tumor necrosis factor)
Diseases named in the same sentence as TNF in open-access papers (continued):
Sharing a sentence is not in itself a finding about the gene and the disease.
tumor (continued). "In a model of azoxymethane (AOM)/DSS colitis-associated cancer, TNF receptor p55-deficient (TNF-Rp55KO) mice presented lower tumor incidence than wild-type (WT) mice." (PMID 33578830, 2021). "pDCs, a TNFα-producing subset of DCs, were found to be very susceptible to the action of Vel, although the role of tumor infiltrating pDCs in immunosuppression or promotion of tumor progression remains unresolved." (PMID 34439244, 2021). "Tumor-associated macrophages loaded with iron can promote the production of ROS and pro-inflammatory cytokines (tumor necrosis factor-α and interleukin-6), thereby inducing tumor cell death in lung cancer." (PMID 34804126, 2021). "The mechanism underlying the anti-tumor activity of iso1Au/TNF and its synergism with Doxo was then investigated." (PMID 33952242, 2021). "B16 melanoma-bearing mice showed a diminished TNF production by tumor-associated myeloid cells after antibiotics treatment and thus responded poorly to immunotherapy." (PMID 34217349, 2021). "Studies revealed that some OVs destroy tumor vasculature via the infection and direct lysis of tumor-associated endothelial cells (ECs) as well as lead tumor cells to inflammatory responses and release of tumor necrosis factor (TNF)-α and interferon (IFN)-γ." (PMID 34563270, 2021). "If loss of cIAP1/2 rendered endothelial cells sensitive to TNF or LTA induced apoptosis or necroptosis then an increase in tumor burden in the lung would be detected." (PMID 33546280, 2021). "Tumor production of TNF-α is associated with poor prognosis, loss of hormone response, and cachexia." (PMID 34079469, 2021). "In NSCLC, it was found that TNFα-induced aerobic glycolysis of TAMs was associated with tumor hypoxia in preclinical and clinical settings." (PMID 33540543, 2021). "In their KPC model, the authors showed that PI3Kα inhibition decreased macrophage differentiation into tumour‐associated inflammatory macrophages and reduced TNF‐α production." (PMID 34057823, 2021). "Any of the UPR sensors can trigger NF-κB-inducing, tumor-promoting, pro-inflammatory cascade implicated in macrophage activation and TNF-α, IL-6, IL-1β, and IL-8 cytokines production." (PMID 34671553, 2021). "The presence of TGF-β and other pro-inflammatory cytokines, such as tumor necrosis factor-alpha (TNF-α), interleukin-6 (IL-6), and IL-8, induce the expression of proteins associated with tumor promotion." (PMID 34178680, 2021). "In both implanted and spontaneous tumours, cGAMP greatly increases TNFα from tumour-associated myeloid cells." (PMID 34285232, 2021). "High levels of TNFα are associated with immune system escape and tumor progression or the development of ICI resistance." (PMID 34855926, 2021). "Specifically, TNF has been known to have multiple associations with carcinogenesis as both a possible enhancer of tumor growth and tumorigenesis in addition to possibly exerting an anti-tumorigenic effect." (PMID 34648530, 2021). "TNF-α is produced by monocytes and macrophages, it can not only regulate the immune function and cause necrosis of some tumor cells, but also mediate pathophysiological reactions such as inflammatory processes, tissue injury and shock." (PMID 35069596, 2021). "While a high concentration of TNFα has been linked to hemorrhagic necrosis, it is now widely accepted that chronic exposure to TNFα is more likely to promote tumor progression." (PMID 34445397, 2021). "Th1 cells produce characteristic cytokines interleukin (IL)-2, interferon (IFN)-γ and tumor necrosis factor (TNF)-α, which primarily mediate anti-tumor immunity and are associated with good prognosis in HCC patients." (PMID 34804916, 2021). "Tumor necrosis factor (TNF) was named in 1975 by Carswell because TNF caused tumor bleeding and necrosis." (PMID 34367136, 2021). "Then, we systematically correlated the TNF risk score with the tumor microenvironment (TME) cell infiltration, molecular subtypes of BLCA, and the potential value for predicting the efficacy of immunotherapy." (PMID 35174161, 2021).
tumor (continued). "TNF-α represents the main regulatory factor for tumor-associated inflammation within TME and plays a vital role in inducing chemokine production and regulating inflammation and immune processes." (PMID 34345201, 2021). "In this study, we mainly analyzed how the mutation status of the TNFα pathway affects the prognosis of ICIs in NSCLC patients from the aspects of tumor immunogenicity and the immune microenvironment." (PMID 34603277, 2021). "The release of the TLR7 agonist together with the release of tumour-associated antigens (TAAs) by dying cancer cells led to DC maturation and the secretion of various cytokines (e.g., TNF-α and IL-6)." (PMID 34073106, 2021). "This response was shown to be dependent on TNF production by tumour-associated myeloid cells followed by a CD8+ T cell response." (PMID 34658896, 2021). "Tumor necrosis factor, a factor in the serum, can kill certain tumor cells or cause blood necrosis in tumor tissues in the body." (PMID 34901283, 2021). "TNF-α is a major factor involved in inflammation-associated cancer and plays an important role in the spread and invasion of tumor cells." (PMID 33953676, 2021). "TNF-α is formed by tumor-associated stromal cells within TME and is involved in diverse chemokine expression as well as the modulation of tumor invasion and metastases." (PMID 34345201, 2021). "TNF-α is an important key mediator of inflammation that has been associated with the promotion of tumor angiogenesis and metastasis." (PMID 34204259, 2021). "TNF produced by myeloid cells was found to promote inflammation-associated tumors, and TNF derived from macrophages was implicated in inflammation and subsequent tumor development." (PMID 34867972, 2021). "TIMP1 deficiency increases either tumor cell sensitivity to chemotherapy or TNF-α-induced apoptosis." (PMID 34737677, 2021). "TNFR1 activation by TNF-α has tumor-promoting action, which is associated with proliferation and activation of NF-κB." (PMID 35177980, 2021). "Now our findings support a new notion that neutrophils exposed to tumor‐derived TNF‐α that activates signals associated with B7‐H2 expression, have displayed a potential to generate inflammatory IL‐17A‐producing Th subsets in GC milieu." (PMID 34185422, 2021). "Increasing concentrations of B. adolescentis also led to increased concentrations of TNF-α, which is cytotoxic to tumor cells but also associated with increased inflammation." (PMID 33803094, 2021). "These NCR+ILC3s were mainly localized at the edge of tumor-associated tertiary lymphoid structures, to produce IL-22, TNF-a, IL-8, and IL-2, and when activated, are able to activate endothelial cells." (PMID 34884995, 2021). "Only a few human fusogens including syncytin-1 and TNF-α have been identified so far to be associated with cell fusion in certain human tumors and cancer cell lines, while their impact on tumor progression is different." (PMID 34572863, 2021). "TNF is implicated in the secondary tumor resistance to epidermal growth factor receptor (EGFR)-blocking therapy by tyrosine-kinase inhibitors of non-small cell lung cancer." (PMID 33917839, 2021). "In the tumor samples, we detected the expression of IL-2 and TNF-α, which is associated with virus replication, confirming delivery of functional virus to the tumor." (PMID 32920593, 2021). "Smac mimetics have been shown to cause tumor cell death in vivo because of exogenous TNF production from innate immune cells." (PMID 33546280, 2021). "M1 tumor‐associated macrophages (TAMs) exert an antitumor function through the secretion of pro‐inflammatory cytokines such as IL‐12, tumor necrosis factor (TNF)‐α, CXCL‐10, and interferon (IFN)‐γ and by increasing the levels of nitric oxide synthase (NOS)." (PMID 33252831, 2021). "Tumor-associated macrophages (TAMs) secrete TNFα to promote tumor cell glycolysis, whereas depletion of TAMs by clodronate is sufficient to abrogate aerobic glycolysis." (PMID 34654454, 2021).
tumor (continued). "TNFα increases PD-L1 expression in murine tumor-associated monocytes and can also improve PD-L1 stability via the NFĸB pathway in cancer cells." (PMID 34445462, 2021). "Splenocytes from mRIPO-treated animals provoked varied tumor-specific lymphocyte states as evidenced by expanded baseline and antigen-specific Th1- (IFNγ, TNF), Th2- (IL-5), and Th9- (IL-9) associated cytokine secretion." (PMID 33767151, 2021). "The role of C. albicans in tumor adhesion and metastasis has been associated with TNF-α and IL-18 18-20." (PMID 33754037, 2021). "The synergism between the peptide vaccine and TNF fusion protein was explained by F8-TNF causing rapid tumor hemorrhagic necrosis and as a result leaving small amount of residual cancer cells." (PMID 34631734, 2021). "RT-PCR analysis revealed that these tumor-infiltrating macrophages expressed higher levels of transcripts encoding IL-1β, IL-12, IL-23, and TNF-α in the AAA-CD4+ group than in the control or auto-CD4+ groups." (PMID 34625113, 2021). "Previously observed direct anti-tumoral properties of TNFα in vivo are among others based on its capacity to hinder tumor-associated blood vessel formation (angiogenesis) via selective endothelial cytotoxicity and necrotic hemorrhage." (PMID 34445397, 2021). "TNFα neutralization decreased serum cytokines, inhibited the development of invasive lesions and reduced tumor-associated neutrophils in vivo." (PMID 34650923, 2021). "It has been shown that tumor necrosis factor-a (TNF-α) production by infiltrating T cells promoted a dedifferentiating process in melanoma cancer cells, thereby leading to tumor antigen loss and an adaptive immune escape mechanism." (PMID 33494181, 2021). "In turn, the antitumor mechanism of TNFα lies in its targeting of the tumor-associated vasculature, causing increased permeability and destruction of the choroid, and as a consequence, leads to the selective accumulation of cytostatic drugs inside the tumor." (PMID 34885171, 2021). "Inflammatory cytokines, including TNF-α and IL-1b, can induce tumour-associated macrophages and endothelial cells to express TF." (PMID 34326419, 2021). "The TNF-alpha has also been reported to be one of the master regulators of tumor-associated inflammation along with IL-6." (PMID 34200663, 2021). "Inflammatory markers such as CRP, TNF-α, and IL-6 are associated with higher tumor grade and risk of mortality in CRC patients and are elevated in the blood of CRC patients compared to healthy controls." (PMID 34239993, 2021). "MSA (3 mg/kg body weight) inhibited tumor growth by up to 61% compared with the control group, which was associated with a decrease in the levels of tumor necrosis factor TNFα and interleukin 6 (IL6)." (PMID 34205571, 2021). "We then developed a nomogram by combining the TNF-based risk score and other clinicopathological characteristics with independent prognostic values in multivariate Cox analysis, including age and tumor stage." (PMID 35174161, 2021). "When apoptosis is blocked, RIP1 will be activated, thereby activating death receptor ligands such as TNF-α and Fas and causing tumor cell necroptosis." (PMID 33526051, 2021). "Several pro-inflammatory cytokines, including IL-6 and TNFα, have been linked to the wasting phenotype in tumor-bearing hosts." (PMID 33014286, 2020). "Tumour-infiltrating CD4+ and CD8+ T cells have been reported to be associated with increased IFN-γ and TNF-α synthesis inducing tumour-specific T cell response." (PMID 32541941, 2020). "It is necessary to further study the association between TNF and efferocytosis in tumors to find effective potential targets, especially in inhibiting tumor metastasis." (PMID 32346605, 2020). "It is also noted that the level of tumor necrosis factor-α (TNF-α) increases in adipose tissue, which is associated with stimulation of tumor endorsement and development of carcinogenesis." (PMID 32454872, 2020).
tumor (continued). "In HCC, NK cells are diminished in tumors compared to non-tumor regions; in addition, they possess a defective IFN-γ and TNF-α secretion caused by the defective recognition of tumor cells, or by inhibitory effects from other immune or cancer cells." (PMID 32235370, 2020). "TNF-α and IL-1β, the major proinflammatory cytokines associated with systemic inflammation, play a critical role in tumorigenesis, tumor progression, and carcinogenesis." (PMID 33050597, 2020). "TNFα has a particular role in enhancing migration and invasion in tumor cells, but the underlying mechanisms are still elusive." (PMID 33187552, 2020). "In these co-cultures of tumour cells and monocytes, we detected upregulation of cytokines (TNFα, MCP-1, IL-10, CXCL-10, IL-1β, IL-6, IL-23) associated with MOv18 IgE ADCC compared to isotype control-triggered cytotoxicity." (PMID 33203088, 2020). "The anti-tumor efficacy of this Lipid A has previously been demonstrated in several models of tumors and was dependent on cytokine secretion (IFNγ, IL-1β and TNFα), iNOS activation and tumor-associated neutrophil (TAN) reprogramming into anti-tumorigenic N1." (PMID 32370259, 2020). "As with IFN-γ cytotoxicity, autophagy genes also regulated TNF sensitivity in this model, with tumor cells with a single mutation in autophagy genes exhibiting increased sensitivity to TNF cytotoxicity." (PMID 33277468, 2020). "In cancer, MDSCs induced the upregulation of IL-10 that downregulates macrophage IL-6 and IL-12 and tumor necrosis factor (TNFα) production, thereby polarizing tumor-associated macrophages (TAMs) toward a tumor-promoting M2 phenotype." (PMID 32983164, 2020). "Aligning the expression of a M1 marker such as TNFα or a M2 marker such as IL-6 with functional activity will help determine the signaling consequences in tumor associated macrophages." (PMID 32318332, 2020). "We provided evidence that patients with TNF-α -308A allele had an increased risk of tumor metastasis." (PMID 32102503, 2020). "Tumor-associated macrophages (TAMs) are a major component of tumor immune cell infiltrates, and are a major source of IL-6 and TNFα in the TME." (PMID 32317968, 2020). "Recently, a homing peptide targeting tumor ECM delivered tumor necrosis factor-α (TNFα) to ECM rich regions in tumors and caused immune cell infiltration and subsequent immune cell-induced ECM breakage." (PMID 32013041, 2020). "Again, using their genetic interaction algorithm, the authors unexpectedly identified that tumor cells with a double mutation in autophagy genes were paradoxically resistant to TNF or CTL killing." (PMID 33277468, 2020). "The expression level of tumor-associated macrophages (TAMs) and proinflammatory cytokines (TNF-α, IL-6) were evaluated by immunohistochemical (IHC)." (PMID 33643891, 2020). "This immunotherapy typically halts tumor growth and induces TNF-dependent hemorrhagic necrosis by tumor-associated myeloid cells leading to tumor suppression." (PMID 32582143, 2020). "On the one hand, a high concentration of TNF-α destroys tumor blood vessels, causes cell necrosis, and also stimulates tumor-specific T cells, which have an antitumor effect." (PMID 32149121, 2020). "SHP-1 deficient CAR19 T cells also secreted more IFNγ, TNFα, and IL-2 and these T cells were more efficient in killing tumor cells in vitro and in vivo." (PMID 33425916, 2020). "TNF-α, IL-6, and IL-17 have known roles in tumor growth and promotion; IL-6 and IL-10 are produced by tumor-associated macrophages and create conditions of immune suppression and angiogenesis." (PMID 32156252, 2020). "On the other hand, previous studies have described that IL-10 deficiency leads to elevated levels of TNF-alpha, IL-6, and IL-17, triggering chronic inflammation and promoting tumor growth." (PMID 32947866, 2020). "Tumor necrosis factor alpha (TNF-α) is an inflammatory cytokine produced by tumor-associated macrophages that can promote tumor growth and progression." (PMID 32733369, 2020).
tumor (continued). "(2016) recently linked Duox-produced ROS from tumor cells to the recruitment of hemocytes, which are activated to secrete the tumor necrosis factor (TNF) ortholog." (PMID 33176146, 2020). "The exact mechanism underlying the antitumor effect of TNF is still poorly understood but several lines of evidence point to a critical role of the TNF‐R1 receptor complex on tumor neovasculature." (PMID 31912630, 2020). "Mast cells produce Th2 cytokines which contributes to M2 (pro-tumor) polarization of tumor-associated macrophages, and the cells produce TNF-α and IL-10 which promote the Treg-mediated immune tolerance and immune tolerance against tumors." (PMID 32023940, 2020). "RNA-seq analysis revealed that RUNX1 was involved in various tumor-associated pathways, such as TNF, mTOR and focal adhesions, and that its downstream targets were involved in proliferation, apoptosis, invasion and epithelial-mesenchymal transition (EMT)." (PMID 32487998, 2020). "An increased concentration of tumor necrosis factor-α (TNF-α) was also associated with the tumor, while the amount of TNF-α in the human body was very low (10–30 pg/mL)." (PMID 33287186, 2020). "The Spearman’s test revealed a high correlation between the immune-related gene signature-based risk score and TNF-α signalling via NF-kB or immune-related pathways, which further confirmed the findings in TCGA tumour tissues." (PMID 32333046, 2020). "TNF-α is one of the most significant molecule causing tumor progression in the tumor vicinity released by MCs." (PMID 33369449, 2020). "KEGG enrichment analysis showed that the pharmacological effects of GQD on CRC are closely related to well-known tumor-associated pathways, including the IL-17, tumor necrosis factor (TNF), Toll-like receptor, and NF-κB signaling pathways." (PMID 33294000, 2020). "Analysis of resected tumour specimens demonstrated that that intratumoural levels of IL‐8, IL‐1β and TNFα were associated with larger tumours and poor differentiation." (PMID 32458441, 2020). "Tumor necrosis factor‐α (TNF‐α) is often found in human tumor tissues and associated with cancer therapy or host response against tumor." (PMID 32392378, 2020). "TNFα is more susceptible to other excreted factors such as VEGF owing to the high complexity of the tumor microenvironment." (PMID 33214550, 2020). "Cytokines, including interleukin-1β (IL-1β), IL-6, tumor necrosis factor-alpha (TNF-α), and chemokines were found to be highly expressed in tumor-associated inflammation." (PMID 33172072, 2020). "These tumor-associated macrophages (TAMs) release a wide variety of cytokines including TNF-α and IL-1β to activate NF-κB in cancer cells and promote Snail1 expression, inflammation, cancer stem cell niches, and all aspects of tumor progression." (PMID 31936290, 2020). "TNFα, which can be released by activated tumor associated macrophages (TAMs), is a major driver of inflammation and one of the main inducers of NF-κB in tumor microenvironment." (PMID 33324403, 2020). "TGF-β1 is a chemokine that can attract macrophages and fibroblasts and cause the release of bFGF, PDGF, TNF-a, and other vasoactive factors, thus promoting angiogenesis and inducing tumor metastasis." (PMID 33488930, 2020). "IL-1β and TNF-α induce VEGF-C expression in tumor-associated macrophages, hence promoting lymphangiogenesis and lymph node metastasis." (PMID 33172072, 2020). "Accordingly, in some cases tumour immune evasion can arise through loss of TNF (tumour necrosis factor‐α) sensitivity, independently of perforin‐mediated killing." (PMID 32419365, 2020). "Except from the myeloid lineage growth factors, TNF supports tumor-associated aberrant myelopoiesis." (PMID 33363012, 2020). "Tumor necrosis factor (TNF) can cause rapid hemorrhagic tumor necrosis in both animal models and patients." (PMID 31912630, 2020).